RHOC (ras homolog family member C)
Diseases named in the same sentence as RHOC in open-access papers (continued):
Sharing a sentence is not in itself a finding about the gene and the disease.
tumor (continued). "To determine the clinical relevance of association of YMO1, RhoC and PAX5 in cancer invasion and metastasis, we validated the experimental results in tumor tissues derived from 153 HCC patients in training cohort." (PMID 27487132, 2016). "We confirmed this observation by showing that the expression levels of RhoC in miR-372-transfected cells and in the tumor tissues of the HSA-372 group of nude mice were downregulated after transfection or injection, respectively." (PMID 26673619, 2016). "RhoC belongs to the highly conserved Ras homologous subfamily, which plays an important role in tumor cell metastasis and invasion." (PMID 26673619, 2016). "Binding of secreted COL1A2 to integrins, such as integrin α2β1 on the surface of tumors, has also been shown to drive tumor cell migration via the activation of RhoC and PI3 kinase." (PMID 27152194, 2016). "Collectively, these results strongly suggest that YMO1 inhibits RhoC expression and its enzymatic activity, through which it suppresses tumor formation and metastasis." (PMID 27487132, 2016). "Inhibition of miR-221 reduced uPAR protein expression and expression of the tumor cell invasion markers vimentin and RHOC." (PMID 25797271, 2015). "Immunofluorescent staining analysis indicated that RhoC expression was decreased in tumor xenografts of mice treated with miR-106b compared to tumor xenografts of saline treated mice." (PMID 25933027, 2015). "Most studies show that RhoC has multiple functions in tumor metastasis, orchestrating the action of multiple downstream effectors, degradation, and reconstruction of the extracellular matrix." (PMID 25649143, 2015). "MiR-93-5P transfection also suppressed tumor development and RhoC expression (determined by immunohistochemistry) in vivo in the xenograft mouse model (p < 0.05)." (PMID 25649143, 2015). "Ras homolog gene family member C (RhoC) is a small G protein/guanosine triphosphatase involved in tumor mobility, invasion, and metastasis." (PMID 25649143, 2015). "Mice injected with PC3 cells transiently depleted of RhoC with siRNA developed less tumour foci in their lungs compared to mice injected with control siRNA‐transfected cells." (PMID 25677806, 2015). "MiR-106b transfection also suppressed tumor development and RhoC expression in vivo in xenograft mouse models." (PMID 25933027, 2015). "IHC staining and OD value indicated that RhoC expression in the tumor xenografts of miR-93-5P–treated nude mice were decreased, and miR-93-5P trasnsfection induced miR-93 mRNA expression while suppressed RhoC mRNA expression in vivo." (PMID 25649143, 2015). "Immunofluorescent staining analysis indicated that RhoC expression in the tumor xenografts of nude mice treated with miR-106b was decreased compared with that in the tumor xenografts of mice treated with saline (the control group)." (PMID 25933027, 2015). "Immunohistochemistry (IHC) and Optical Density Value indicated that RhoC expression in the tumor xenografts of miR-93-5P–treated nude mice were decreased compared with that in mock nude mice." (PMID 25649143, 2015). "In our pilot study, we detected the expression of 4 proteins which were closely related with the invasive potential of tumor cells, including vimentin, RhoA, RhoC and MMP-2." (PMID 24658581, 2014). "RhoB differs from the other GTPases RhoA and RhoC in that it is postulated to be a tumor suppressor because its expression is decreased in a number of tumor cell types." (PMID 25548921, 2014). "Altogether, these studies strongly suggest RhoC is a pro-metastasis oncogene that plays a significant role in transforming non-invasive tumor cells into an invasive phenotype." (PMID 24533098, 2014). "The presence of GFP expression and the knockdown of RhoC expression in UM-SCC-1 has been published in our earlier studies on the effect of RhoC inhibition on cell invasion and tumor formation in mice." (PMID 24533098, 2014).
tumor (continued). "In vivo functional investigations indicated that RhoC, although dispensable for embryonic/postnatal development and tumor initiation, was critical for tumor metastasis." (PMID 24312560, 2013). "Our recent study demonstrated that RhoC was a key regulator of tumor cell growth and apoptosis in HCC cells." (PMID 23382905, 2013). "We propose that RhoC facilitates tumor cell invasion and promotes subsequent metastasis, in part, by enhancing integrin α5β1 trafficking." (PMID 24312560, 2013). "We have shown previously that PRL-3 promotes activation of the small GTPase RhoC, which contributes to tumor cell motility and invasion through regulation of the actin cytoskeleton." (PMID 23691193, 2013). "Expression of RhoC mRNA levels in tumor tissues collected from HCC patients were significantly higher than that of the para-cancerous normal liver tissues." (PMID 23382905, 2013). "Among various members of the Rho family proteins, RhoC is suggested to be dispensable for embryogenesis and tumor initiation but essential for tumor metastasis." (PMID 23382905, 2013). "In contrast, two mice (n = 5) exhibited obvious tumor formation after inoculation of HL7702 cells stably expressing RhoC." (PMID 23382905, 2013). "Accumulating evidences highlight the critical role of RhoC in tumor metastasis, and our current study provide valuable insights into understanding the complex actions of RhoC in regulating biological activities of tumors." (PMID 23382905, 2013). "Future studies will focus on an investigation of the molecular mechanisms that drive TEM4- and RhoC-dependent endothelial and tumor cell migration and invasion to regulate tumor progression." (PMID 23825001, 2013). "This indicated that RhoC drove tumor proliferation through IQGAP1, specifically through the C-terminal fragment of IQGAP1." (PMID 23145020, 2012). "Most of the studies showed that RhoC had multiple functions in tumor metastasis, orchestrating the action of multiple downstream effectors, degradation and reconstruction of the extracellular matrix (ECM)." (PMID 23145020, 2012). "OPN supports tumor angiogenesis, invasion and metastasis and the GTPase RHOC plays a fundamental role in cytoskeleton-dependent processes including alterations in cell shape, polarity, adhesion, cell motility and cell to matrix interactions." (PMID 22895562, 2012). "Knocking down RhoC in SUM149 cells significantly decreased tumor incidence in the ALDH (+) population." (PMID 22911725, 2012). "Mechanistic studies reveal that PRL-3 functions as an initiator of neoplastic angiogenesis by recruiting endothelial cells and stimulates invasion and motility of tumor cells through activating the Rho family of small GTPases such as RhoA and RhoC." (PMID 21589872, 2011). "We show that RhoC drives tumour progression by regulating invasion, metastasis, tumour growth and angiogenesis." (PMID 19953094, 2010). "To determine the contribution of RhoC to tumour growth, we used (5 × 106 cells) stable clones of CaSki and SiHa cells expressing dnRhoC and wtRhoC, respectively, and generated xenografts in nude mice over a period of 21 days." (PMID 19953094, 2010). "Immunohistochemical analyses of tumor xenograft sections also revealed the decreased RhoA and RhoC expression in Ad-RhoA-RhoC group." (PMID 20828398, 2010). "Immunohistochemical assessment of archival tissue sections showed expression of RhoC, Vegf and Hifα in the same areas of tumour sections." (PMID 19953094, 2010). "The levels of RhoA and RhoC mRNA transcripts and proteins in tumor xenografts were detected by reverse quantitative transcription polymerase chain reaction (QRT-PCR) and immunohistochemical staining respectively." (PMID 20828398, 2010). "In this study, we show that RhoC regulates EMT during tumour progression in a manner similar to Notch1." (PMID 19953094, 2010).
tumor (continued). "RhoC activity has been shown to reduce EMT-induced migration and also to regulate E-cadherin expression and is specifically implicated in IBC tumor progression." (PMID 20808935, 2010). "In Ad-RhoA-RhoC group, the cancer cells of tumor tissues stained very weakly for RhoA and RhoC, in comparison with NS group and Ad-HK group." (PMID 20828398, 2010). "Although cytoplasmic expression of RhoC was observed in all the cases across all grades of tissues, the percentage of positive cases increased across the tumour grades." (PMID 19953094, 2010). "As phenotypically both Notch and RhoC signalling molecules regulate similar features during tumour progression, we explore the possibility of RhoC being a downstream effector of Notch1." (PMID 19953094, 2010). "The ectopic expression of RhoC and its mutant altered the tumour growth properties of CaSki and SiHa cells." (PMID 19953094, 2010). "Representative images suggest an expression of RhoC, Hifα and Vegf in the same area of the tumour with negligible immunodetection in normal cervix tissues suggesting a co-expression of these molecules." (PMID 19953094, 2010). "Considering that both Notch1 and RhoC regulate similar features during tumour progression, we explored the possibility of cross-talk between Notch1 and RhoC." (PMID 19953094, 2010). "RhoA participates in oncogenic transformation whereas RhoC promotes tumor metastasis and cell migration." (PMID 19319183, 2009). "Overexpression of RHOC is associated with the loss of expression of WISP3, which acts as a tumor suppressor." (PMID 18230143, 2008). "Other studies have shown that the stimulatory effect of the RhoC GTPase-activity on tumour growth depends on NF-κB activity." (PMID 17700572, 2007). "This study also presents a fresh link to the regulation of RhoC-mediated migration and invasion, giving a functional role for RhoC in PC tumor cells." (PMID 15969750, 2005). "Our present study also showed that extrahepatic metastasis of HCC expressed significantly higher RhoC levels than intrahepatic HCC, and elevated expression of RhoC positively correlated with vein invasion, and the number of tumour nodes." (PMID 15150600, 2004). "There is a highly significant correlation of the RhoC expression levels with tumour vein invasion, number of tumour nodes and the status of differentiation." (PMID 15150600, 2004). "As compared to the normal tissue, about 10–30% of the tumours revealed either enhanced levels of rhoB and rhoC mRNA or even reduced levels of rhoA and rac1 mRNA." (PMID 12237774, 2002). "RhoC vaccine can induce effective and durable T cell immunity, which may delay or prevent tumor recurrence and metastasis formation." (PMID 40145100, 2025). "Furthermore, concomitant treatment with FDA-approved dacarbazine and simvastatin or fluvastatin suppressed both tumor growth and metastasis in murine models by attenuating the RhoA/RhoC pathway." (PMID 38540310, 2024). "In conclusion, BCL6 expression and its tumor suppressor role in GC could be strengthened by RNF180/RhoC pathway." (PMID 37060074, 2023). "In addition, RhoA and RhoC are carcinogenic and related to cell proliferation, migration, and invasion, whereas RhoB is a tumor suppressor and promotes cell apoptosis." (PMID 36320006, 2022). "The H&E staining of tongue showed that compared to control mice the injection of tumor cells could lead to epithelial hyperplasia: the degree of epithelial cell proliferation was significantly lower in the RhoC/shRNA group than in the control group." (PMID 33519932, 2021). "The significant role of RhoC in tumor metastasis suggests that it may have great potential as a target for anti-metastasis therapy." (PMID 34627249, 2021). "In addition, RhoC improves cell motility, which consequently results in a greater ability of the tumor to become invasive." (PMID 33946718, 2021). "The results of TCGA analysis showed that RhoC was overexpressed in OSCC tumor tissues." (PMID 33519932, 2021).
tumor (continued). "It is known that there is a connection between the increase in RhoC expression and an advanced stage of the tumor as well as with the presence of metastases; to which certain crosstalk with angiogenic factors such as vascular endothelial growth factor (VEGF) also contributes." (PMID 33946718, 2021). "Taken together, studies have also suggested that the inhibition of RHOC through gene regulators such as lncRNAs may be a new therapeutic target to abolish advanced tumor phenotypes." (PMID 34771549, 2021). "Blockage of the RhoC downstream signaling by small molecule inhibitors may represent a potent treatment strategy to inhibit tumor invasion and migration." (PMID 32443784, 2020). "Apparently, knockdown of RhoC suppressed tumor proliferation and invasion." (PMID 33082325, 2020). "In summary, our findings suggest that RNF180 could reduce tumor metastasis in GC by inhibiting STAT3 activation via RhoC protein degradation through the ubiquitin–proteasome system." (PMID 33082325, 2020). "Indeed, a novel RhoC antagonist delayed the onset of the primary tumor in a PyMT-RhoC transgenic mouse model and reduced primary tumor growth and lung metastasis compared with control mice." (PMID 32883032, 2020). "The activity and the spatial distribution of RhoC represent a critical route by which tumor cells control the recruitments of cortactin, TKS5, and matrix proteases in the formation of invadopodia precursors, and the spatial restriction of cofilin activity, starting the maturation process." (PMID 33178698, 2020). "Furthermore, the elevated mRNA expression of RhoA and RhoC was accompanied by higher tumor stages and metastatic spread." (PMID 32443784, 2020). "Ras Homolog Family Member C/Tumour cell proliferation and metastasis." (PMID 32888398, 2020). "Also, it is a vital regulator of cell migration, proliferation, and apoptosis, and therefore, inhibition of RhoC results in suppressing the tumor invasion and metastasis." (PMID 31905344, 2020). "This cascade, starting with the interaction of β-arr1 with PDZ-RhoGEF, controlling the spatial distribution of RhoC GTPase and cofilin pathway, represents a critical route by which the tumor cells form active invadopodia, and acquires maximally proinvasive capabilities." (PMID 30837880, 2019). "RhoC therefore plays an important role at various stages of tumor progression." (PMID 31340863, 2019). "Studies also suggest that the inhibition of RhoC results in abolition of advanced tumor phenotypes." (PMID 31340863, 2019). "HXOD10 suppressed the tumor growth and detected an opposite trend of protein RHOC." (PMID 30683109, 2019). "Resultantly, it is apt to believe that RhoC may be involved in regulating or maintaining tumor plasticity, which endows adaptability at every stage of tumor progression." (PMID 31340863, 2019). "Likewise, miR-372 over-expression led to G1 arrest and apoptosis, along with a suppression of tumor growth and the metastasis of endometrial carcinoma via inhibition of RhoC." (PMID 31340863, 2019). "RhoC has also been shown to contribute to therapy resistance in some tumor models." (PMID 31340863, 2019). "After 2 weeks of implantation, when the mice had a tumor volume of 20 mm3, the mice were treated with 100 μL of anti-RhoA (85 nM), anti-RhoC (85 nM) siRNA and cytofectin containing excipient as a control intratumarally at a 3-day interval over a period of 20 days." (PMID 29861465, 2018). "RhoA and RhoC are the key drivers for a series of pathologies of cancer, including cell motility, proliferation, apoptosis inhibition, cell cycle progression, invasion, metastasis and inflammation of tumor cells." (PMID 29861465, 2018). "S1PR2 is also involved in negative regulation of tumor angiogenesis and tumor growth in vivo via RhoC activation, although one study has shown that the growth of SKOV3 cells could be decreased by S1PR2 inhibition in vitro and in vivo." (PMID 29987226, 2018).
tumor (continued). "In the present study, we have tried to determine whether the lncRNA ABHD11-AS1 affects tumor growth and progression via regulation of RhoC expression." (PMID 28818073, 2017). "Data from the literature indicate that RhoC expression may occur at selective stages of tumor progression and metastasis." (PMID 29152087, 2017). "The next key question is whether YMO1-mediated suppression of tumor invasion and metastasis depends on its inhibitory effect on RhoC activity." (PMID 27487132, 2016). "Intriguingly, they also showed that deficiency of RhoC does not affect tumor angiogenesis by investigating the levels of CD31 and Factor VIII expression in primary tumors in their mouse model." (PMID 26742562, 2016). "RhoC has been shown to regulate tumor progression, in several tumors." (PMID 27597870, 2016). "Interestingly, RhoC regulates several tumor phenotypes including angiogenesis, anoikis resistance, migration, invasion, and metastasis." (PMID 27597870, 2016). "This study suggests that targeting of RhoA alone may allow for compensation and a paradoxical exacerbation of neoplasia, while simultaneous targeting of both RhoA and RhoC is likely to lead to more favorable outcomes." (PMID 26030593, 2015). "Several previous studies of the relationship between RhoA and Ras signaling in cell transformation prompted our current investigation of whether RhoA or RhoC are required for K-Ras-induced tumor formation." (PMID 26030593, 2015). "Our investigation of these genetic studies produced surprising results that individually RhoA and RhoC are dispensable for the oncogenic K-Ras induced lung tumorigenesis and loss of RhoA alone exacerbates, rather than suppresses, tumor initiating activity." (PMID 26030593, 2015). "These are further indications that miR-106b might suppress tumor proliferation and metastasis by targeting RhoC." (PMID 25933027, 2015). "RhoC is a small G protein/GTPase and involved in tumor mobility, invasion and metastasis." (PMID 24986540, 2014). "Therefore, it is likely that RhoA and RhoC represent a subset of proteins important for tumor cell invasion that are affected by PFIs and that protein prenylation in general remains the primary target of PFIs." (PMID 24587105, 2014). "In contrast, knockdown of RhoC expression efficiently inhibited tumor cell proliferation." (PMID 23382905, 2013). "By contrast to RhoA and RhoC reported to be up-regulated in several types of cancers, RhoB displays a property that may participate in tumor suppression." (PMID 24223801, 2013). "Clinical relevance of RhoC expression in HCC tumor and adjacent normal liver tissues." (PMID 23382905, 2013). "A later study indicated that RhoC is dispensable for tumor initiation but essential for metastasis." (PMID 22200848, 2012). "RhoC increases with the decrease of HOXD10 leading to tumor cell invasion and metastasis." (PMID 22200848, 2012). "Therefore, further study is needed to identify the role of RhoC in regulating biological activities of tumor cells." (PMID 23145020, 2012). "We thus propose RhoC as downstream effector of Notch1 during tumour progression." (PMID 19953094, 2010). "There is emerging evidence that RhoC regulates features of tumour progression." (PMID 19953094, 2010). "Phosphatase of regenerating liver-3 (PRL-3) is a newly identified proteintyrosine phosphatase, which belongs to phosphatase of regenerating liver family, and plays a role in promoting tumor metastasis; Ras homologue C (RhoC) belongs to Rho subfamily of small-molecule G protein superfamily." (PMID 20681446, 2010). "And further research work should be done to examine the downstream effectors of RhoA and RhoC; such as ROCK-I and ROCK-II, being most associated with metastasis and progress in cancer, which will be benefit for exploring the possible molecular mechanisms of RhoA and RhoC in tumor inhibition." (PMID 20828398, 2010). "Do Notch1 and RhoC regulate similar function during tumour progression?" (PMID 19953094, 2010).